STC2 (stanniocalcin 2)
Diseases named in the same sentence as STC2 in open-access papers (continued):
Sharing a sentence is not in itself a finding about the gene and the disease.
lymph node metastasis (15 papers, 2013 to 2025). "Additionally, STC2 expression was significantly associated with lymph node metastasis, lymphatic invasion, and long-range metastasis (P = .005.007, and .038, respectively)." (PMID 35945754, 2022). "STC2 is also associated with lymph node metastasis in esophageal cancer patients." (PMID 35935989, 2022). "An increased expression of STC2 was also associated with lymph node metastasis." (PMID 34612765, 2021). "This prognostic value extends to pan-cancer analysis, where STC2 expression levels were significantly elevated in various cancer types, particularly in advanced stages and lymph node metastasis samples." (PMID 40535801, 2025). "Recently STC2 was identified as a predictive marker for lymph node metastasis in esophageal squamous-cell carcinoma." (PMID 24855559, 2014). "The high expression of STC2 was correlated with lymph node metastasis, lymphatic invasion, tumor depth, tumor size, AJCC stage classification and worse overall survival rates." (PMID 23548070, 2013). "A previous study regarded STC2 as a predictive marker for lymph node metastasis in ESCC." (PMID 35497331, 2022). "The dysregulation of STC2 was reported as a major risk factor of EGFR tyrosine kinase inhibitor (TKI) resistance in non-small cell lung cancer (NSCLC) and a predictive marker for lymph node metastasis in esophageal squamous cell carcinoma." (PMID 36589233, 2022). "The expression of STC2 mRNA and protein in poor differentiation group and lymph node metastasis group was significantly higher than that in the high and moderate differentiation group and without lymph node metastasis group." (PMID 30962272, 2019).
nasopharyngeal carcinoma (14 papers, 2014 to 2024). A carcinoma arising from the nasopharyngeal epithelium. "STC2 overexpression was associated to nasopharyngeal carcinoma malignancy and poor prognosis including higher potential of progression and distant metastasis." (PMID 32296395, 2020). "STC2 overexpression is associated with a poor prognosis in patients with nasopharyngeal carcinoma (NPC) and can be used as a predictor of NPC responses to radiation." (PMID 33167940, 2020). "To explore the effect of STC2 on the pathogenesis of nasopharyngeal cancer, we performed RNA-seq on STC2 knockdown cell line CNE1 and its control cells." (PMID 33797657, 2022). "We monitored the activity of CNE1 cells and changes of SIV in zebrafish embryo nasopharyngeal cancer model by the use of epifluorescent microscopy and found that STC2 knockdown obviously suppressed the proliferate of cancer cells in zebrafish." (PMID 33797657, 2022). "The results showed that the STC2 was upregulated in primary nasopharyngeal carcinoma tissues than normal tissues." (PMID 33797657, 2022). "In summary, we found that STC2 was highly expressed in primary nasopharyngeal carcinoma tissues and lymph node metastatic tissues." (PMID 33797657, 2022). "We found that STC2 was highly expressed in primary nasopharyngeal carcinoma tissues and lymph node metastatic tissues." (PMID 33797657, 2022). "In another study of our laboratory, we found glucose-deprivation can induce STC2 at protein levels in CNE2 nasopharyngeal carcinoma cells." (PMID 35501821, 2022). "Another study utilized human CNE2 nasopharyngeal carcinoma cells to investigate the mechanism of how STC2 mediates the development of acquired resistance to radiation." (PMID 35501821, 2022). "Based on the results from our study, we propose a schematic diagram of STC2 in the regulation of nasopharyngeal carcinoma." (PMID 33797657, 2022). "It has been reported that STC2 promotes nasopharyngeal carcinoma cell migration and invasion and that it is an oncogene." (PMID 34249085, 2021). "Using CNE2 cell line model as well as tumor samples from 94 patients, it was shown that STC2 promoted post-radiation survival, migration, and invasion of nasopharyngeal carcinoma." (PMID 32296395, 2020). "To assess the role of STC2 in human nasopharyngeal carcinoma, we first determined the expression levels of STC2 in normal tissues, primary carcinoma tissues, and lymph-node metastatic tissues of human nasopharyngeal carcinoma." (PMID 33797657, 2022). "Furthermore, STC2 was also significantly upregulated in lymph node metastasis than nasopharyngeal carcinoma tissues." (PMID 33797657, 2022). "We not only found its high expression in primary nasopharyngeal carcinoma tissues and lymph-node metastatic tissues, but also found that STC2-mediated regulation of EMT and glycolysis traits was partially realized through the modulation of ITGB2/FAK/SOX6 signaling." (PMID 33797657, 2022). "Then, we explored the prognostic value of STC2/ITGB2/SOX6 in nasopharyngeal carcinoma." (PMID 33797657, 2022). "High expression of STC2 could also enhance the ability of migration and invasion for nasopharyngeal cancer cells after radiotherapy." (PMID 34079579, 2021). "Therefore, STC2 possesses predictive value in nasopharyngeal cancer patients and may serve as a therapeutic target to overcome radiation resistance and metastasis." (PMID 34612765, 2021). "Taken together, STC2 can participate in EMT and glycolysis in nasopharyngeal cancer by regulating their related genes." (PMID 33797657, 2022). "However, the role of STC2 in the regulation of nasopharyngeal carcinoma (NPC) remains poorly understood." (PMID 33797657, 2022). "To explore the function of STC2 in nasopharyngeal cancer, we detected the cell viability by CCK-8 and found that STC2 knockdown led to decreased proliferative capacity in 6-10B and CNE1 cells." (PMID 33797657, 2022). "Moreover, STC2 could promote glycolytic process in nasopharyngeal carcinoma." (PMID 35924040, 2022).
nasopharyngeal carcinoma (continued). "To further explore the mechanism of STC2 in nasopharyngeal cancer, we analyzed GSEA results upon STC2 knockdown RNA-seq data and identified integrins and FAK signal pathway as potential downstream targets." (PMID 33797657, 2022). "In order to further clarify whether STC2 is involved in tumor growth, the STC2 knockdown cell line CNE1 and its control cell line were used to establish the zebrafish embryo nasopharyngeal cancer model and nude mice model." (PMID 33797657, 2022). "However, the clinical significance of STC2 overexpression in nasopharyngeal carcinomas (NPC) has not been investigated." (PMID 24606961, 2014).
renal cell carcinoma (13 papers, 2013 to 2025). "Our study found that STC2 is mutated in most cancers, and the frequency of STC2 gene mutation in renal cell carcinoma patients reached 15.2%; most of the alterations were amplification." (PMID 35937984, 2022). "STC2 is overexpressed across a range of cancers, including bladder, colon, esophagus, liver, lung, ovary, pancreas, prostate, rectum, renal cell carcinoma, skin, testis, thyroid, and uterus." (PMID 40006048, 2025). "Among them, renal cell carcinoma patients had the highest frequency of STC2 gene alteration (15.82%) and the most alterations were amplification (15.44%, 82/531)." (PMID 35937984, 2022). "Increased cytoplasmic STC2 expression correlated to aggressiveness of renal cell carcinoma and shorter overall patient survival times." (PMID 24606961, 2014). "STC2 was upregulated at the mRNA and protein levels in renal cell carcinoma." (PMID 23548070, 2013). "The level of STC2 mRNA and protein were increased in the tissues of renal cell carcinoma (RCC)." (PMID 34612765, 2021).
cervical cancer (12 papers, 2016 to 2025). A primary or metastatic malignant neoplasm involving the cervix. "We have also shown that high STC2 expression was associated with chemoradiotherapy failure in our cohort, implying that STC2 might be a useful prognostic hypoxia biomarker in cervical cancer." (PMID 27244197, 2016). "The expression of STC2 in cervical cancer tissues and cell lines was upregulated, and this was correlated positively with cell proliferation." (PMID 34612765, 2021). "Similarly, STC2, which was also upregulated in multiple drug resistance profiles, has been found to be significantly elevated in cisplatin resistant cervical cancer cells." (PMID 37384294, 2023). "In cisplatin-resistant cervical cancer cells, the expression of STC2 was significantly increased." (PMID 34612765, 2021). "Moreover, STC2 is a promising prognostic hypoxia biomarker in cervical cancer." (PMID 27244197, 2016). "Therefore, STC2 may be a prognostic marker in cervical cancer patients undergoing radiotherapy." (PMID 34612765, 2021). "In addition, other two lncRNAs are reported to regulate STC2 expression, for example, ROR1-AS1 functions to sponge miR-670-3p that suppresses STC2 expression in cervical cancer; SNHG17 promotes STC2 expression through antagonizing the activity of miR-361-3p in rectal cancer." (PMID 35501821, 2022).
osteosarcoma (12 papers, 2020 to 2024). A usually aggressive malignant bone-forming mesenchymal neoplasm, predominantly affecting adolescents and young adults. "In conclusion, we have proposed an ER stress risk model as an independent prognostic factor and identified STC2 as a novel risk indicator for disease progression, providing a promising direction for further research and treatment of osteosarcoma." (PMID 39119088, 2024). "In this study, we developed a novel ER stress-related prognostic signature (ERSRPS) for osteosarcoma based on five differentially-expressed ERSRGs; among them, Stanniocalcin 2 (STC2) was determined to be the risk gene associated with an unfavorable prognosis in ER stress signaling." (PMID 38229155, 2024). "Using multiple bioinformatic analysis and local hospital samples validation, we revealed the gain of expression of STC2 in osteosarcoma, which associated statistical significantly with patients survival, and the gene’s clinical features and potential biological functions were also explored." (PMID 36803385, 2023). "In this study, we demonstrated that STC2 expression was upregulated in osteosarcoma tissues, which was correlated with a poorer survival." (PMID 38229155, 2024). "We also validated the critical significance of the endoplasmic reticulum stress-related gene STC2 in osteosarcoma, providing promising insights for the mechanistic understanding and treatment of osteosarcoma." (PMID 39119088, 2024). "The qRT-PCR results revealed that STC2 expression levels in osteosarcoma cells were much higher than in osteoblasts." (PMID 38460960, 2024). "The ER stress related gene STC2 was found to be highly expressed in osteosarcoma, and STC2 knockdown significantly inhibited the proliferation and migration of osteosarcoma cells." (PMID 38229155, 2024). "By immunohistochemistry staining, we identified a difference in STC2 expression in three pairs of osteosarcoma tissues and adjacent control tissues, and the results were comparable with the mRNA data." (PMID 38460960, 2024). "STC2 knockdown also resulted in the upregulation of MHC-I molecule expression in osteosarcoma cells and the restoration of CD8+ T cells activation." (PMID 38229155, 2024). "Subsequently, through IHC staining with a large number of samples, we analyzed the high expression of STC2 in osteosarcoma patients." (PMID 39119088, 2024). "The STC2 expression in osteosarcoma specimens and control tissue was compared using two separate datasets from the GEO database (GSE225588 and GSE99671)." (PMID 38460960, 2024). "Meanwhile, as for the STC2 expression in different subtypes of osteosarcoma, the result indicated that it expresses higher in chondroblastic and osteoblastic osteosarcoma than fibroblastic and telangiectatic osteosarcoma." (PMID 36803385, 2023). "Although previous study also reported the potential regulation of STC2 on osteosarcoma survival, comprehensive and deeper analysis are still needed to confirm the regulatory role of STC2 in osteosarcoma development." (PMID 36803385, 2023). "Before further exploring the detailed biological function of STC2 gene in osteosarcoma progression, ProtParam and ProtScale were combine used to interpret the basic physicochemical property of STC2 gene." (PMID 36803385, 2023). "Given the importance of the specific osteoid extracellular matrix formation in clinical diagnosis of osteosarcoma, we mainly focused on STC2 gene for further analysis." (PMID 36803385, 2023). "Firstly, the analysis result of CCLE which has been a well known online database for cancer cell lines researches also supported that STC2 expresses much higher in chondrosarcoma and osteosarcoma cell lines comparing to other cancers and sarcomas." (PMID 36803385, 2023). "The results of the cell further identified that the expression levels of PREB and STC2 were higher in osteosarcoma cells than in normal osteoblasts, while TSPYL2 and ATP6V0D1 exhibited the opposite results." (PMID 35754801, 2022).
osteosarcoma (continued). "ST3GAL4, TRIM8, STC2, TRPS1, and FAM207A are high-risk genes that are involved in the occurrence and development of osteosarcoma." (PMID 35102149, 2022). "Next, to assess the role of UPRRGs in predicting the prognosis of osteosarcoma, we constructed a prognostic signature to predict the survival of osteosarcoma patients via four genes (STC2, PREB, TSPYL2, and ATP6V0D1)." (PMID 35754801, 2022). "The risk heat map showed that the gene expression of ST3GAL4, TRIM8, STC2, TRPS1, and FAM207A increased from low-risk to high-risk groups, indicating that the five genes in this study were related to osteosarcoma." (PMID 35102149, 2022). "Recently, a study with bioinformatic analysis found STC2 can be grouped with glycolytic genes to assess the prognosis of patients with osteosarcoma." (PMID 35501821, 2022). "In osteosarcoma, STC2 was reported to promote the proliferation, invasion and migration of osteosarcoma cells by enhancing the glycolysis." (PMID 34079579, 2021). "Furthermore, the ER stress-related gene STC2 was found to downregulate the expression of MHC-I molecules in osteosarcoma cells, and mediate immune responses through influencing the infiltration and modulating the function of CD8+ T cells." (PMID 38229155, 2024). "Targeting STC2 significantly suppressed the growth and metastasis of osteosarcoma cells." (PMID 38229155, 2024). "Additionally, we discovered Stanniocalcin-2 (STC2) as a significant prognostic gene highly expressed in osteosarcoma and potential disease biomarker." (PMID 38460960, 2024). "STC2 expression was shown to be significantly upregulated in osteosarcoma specimens." (PMID 38460960, 2024). "Additionally, STC2 knockdown significantly inhibited osteosarcoma cell proliferation, migration, and invasion." (PMID 38229155, 2024). "The changed cellular location in osteosarcoma indicated that STC2 participate in osteosarcoma development via specific mechanisms for example interacting with nuclear locating transcription factors or regulators which is certainly an inspiring direction for further research." (PMID 36803385, 2023). "Besides the IHC experiment, Oncomine online analysis also supported that although STC2 expression was broad spectrum up regulated in multiple sarcomas, the expression was higher in osteosarcoma than other tumors." (PMID 36803385, 2023). "STC2 gene was selected base on previous GEO data exploration combined with further survival analysis which results supported that STC2 was one of the genes that were high level differential expression in osteosarcoma comparing to normal control samples and related with patients survival." (PMID 36803385, 2023). "Finally, four genes (STC2, PREB, TSPYL2, and ATP6V0D1) were screened to construct and validate a risk signature to predict the prognosis of patients with osteosarcoma." (PMID 35754801, 2022). "Finally, based on the results of previous screening, four UPRRGs (STC2, PREB, TSPYL2, and ATP6V0D1) were identified to establish a risk model for osteosarcoma via the multivariate Cox regression analysis." (PMID 35754801, 2022). "Additionally, western blotting revealed that STC2 was up-regulated in osteosarcoma cells." (PMID 38229155, 2024). "Furthermore, STC2 was found to modulate osteosarcoma cell proliferation, apoptosis, and EMT." (PMID 38460960, 2024). "Notably, our study revealed a remarkable increase in MHC-I molecules following STC2 knockdown in osteosarcoma cells, implying that STC2 may mediate immune response by downregulating the expression of MHC-I molecules on the surface of tumor cells." (PMID 38229155, 2024). "Inspired by above especially IHC experiment results, to preliminary explore the potential mechanism of STC2 regulation on osteosarcoma development, the PPI network of STC2 centered genes was constructed." (PMID 36803385, 2023).
osteosarcoma (continued). "The results showed that the expression levels of ST3GAL4, TRIM8, STC2, TRPS1, and FAM207A genes were significantly higher in the osteosarcoma cell line compared to that in the normal human osteoblasts." (PMID 35102149, 2022). "The results revealed that the expression levels STC2 and PREB were elevated clearly in osteosarcoma tissues than in normal tissues, whereas the ATP6V0D1 expression level was significantly downregulated in tumor tissues compared with normal tissues." (PMID 35754801, 2022). "We performed qRT-PCR to detect the expression of ST3GAL4, TRIM8, STC2, TRPS1, and FAM207A genes in normal human osteoblasts (hFOB1.19) and osteosarcoma cells (MG63 and SJSA-1)." (PMID 35102149, 2022). "In this study, we explored the role of four genes (EFNA1, P4HA1, STC2, and MAFF) profiled in a previous study on osteosarcoma." (PMID 34337075, 2021). "We found that STC2 and CD8+ T cells showed a significant negative correlation trend, indicating that STC2 promoted the occurrence and development of osteosarcoma by inhibiting CD8+ T cells." (PMID 35102149, 2022). "Our findings suggested that ST3GAL4, TRIM8, STC2, TRPS1, and FAM207A could be used as potential biomarkers for the prognosis of patients with osteosarcoma." (PMID 35102149, 2022). "We examined 198 glycolysis-related genes that showed differential expression in metastatic and non-metastatic osteosarcoma samples in the TARGET database, and identified three genes (P4HA1, ABCB6, and STC2) for the establishment of a risk signature." (PMID 33952718, 2021). "High expression of STC2 and RASGRP2 were correlated with poor prognosis of osteosarcoma." (PMID 34079579, 2021). "Additionally, we identified that ER stress related gene STC2 promoted the malignant development and metastasis in osteosarcoma, and modulated immune responses by reducing MHC-I molecule expression in osteosarcoma cells and impairing CD8+ T cell function within the TME." (PMID 38229155, 2024). "Finally, we found Stanniocalcin-2 (STC2), a crucial prognostic gene that has significant expression in osteosarcoma and could serve as a promising biomarker for the disease." (PMID 38460960, 2024). "Therefore, we speculate that STC2 and TNFRSF11B may play a more critical role in the progression of osteosarcoma." (PMID 39119088, 2024). "Additionally, the result of qRT-PCR which was conducted using 20 local hospital osteosarcoma and paired normal bone tissues supported the STC2 gain of expression in cancer (data not shown)." (PMID 36803385, 2023). "Therefore, we suggested that ST3GAL4, TRIM8, STC2, and FAM207A genes could regulate the immune microenvironment of osteosarcoma by influencing cytokines to promote tumor growth and invasion." (PMID 35102149, 2022). "Additionally, IHC staining revealed a negative correlation between STC2 expression and the expression of MHC-I molecules in our osteosarcoma cohort." (PMID 38229155, 2024).